MTND2P28 (MT-ND2 pseudogene 28)
Gene: Unprocessed pseudogene on chromosome 1 (629,640 to 630,683, forward strand). Ensembl gene ENSG00000225630.
Diseases named in the same sentence as MTND2P28 in open-access papers:
MTND2P28 is named in the same sentence as 1 disease in open-access papers, as found by Europe PMC text mining. Sharing a sentence is not in itself a finding about the gene and the disease. The quoted sentences say what the papers report.
schizophrenia (1 paper, 2024). A major psychotic disorder characterized by abnormalities in the perception or expression of reality. "From total 66 DEGs, we identified 11 (16%) as pseudogenes, which comprised two main groups: mitochondrial pseudogenes increased in females (MTND1P23, MTCO1P12, MTCO1P40, and MTND2P28) and ribosomal pseudogenes increased in male schizophrenia patients (RPS4XP22, RPS16P4, and RPS28P7)." (PMID 39068467, 2024).